HYAL2 (hyaluronidase 2)
Diseases named in the same sentence as HYAL2 in open-access papers (continued):
Sharing a sentence is not in itself a finding about the gene and the disease.
cleft lip (2 papers, 2018 to 2022). Congenital defect in the upper lip where the maxillary prominence fails to merge with the merged medial nasal prominences. "The clinical and genetic studies described herein establish HYAL2 gene variants as a cause of syndromic cleft lip and/or palate, and our molecular findings identify HYAL2 protein deficiency as the pathomolecular basis of disease." (PMID 34906488, 2022).
congenital heart anomaly (2 papers, 2017 to 2022). "We previously defined biallelic HYAL2 variants causing a novel disorder in 2 families, involving orofacial clefting, facial dysmorphism, congenital heart disease, and ocular abnormalities, with Hyal2 knockout mice displaying similar phenotypes." (PMID 34906488, 2022). "We describe mutations in an enzyme involved in the development of the palate and heart (Hyaluronidase 2, HYAL2) as the cause of a syndrome of CLP and a congenital heart anomaly (cor triatriatum sinister, CTS) in families from the Amish community and Northern Saudi Arabia of Arabic ethnicity." (PMID 28081210, 2017).
diffuse large B-cell lymphoma (2 papers, 2009 to 2017). "Very recently, copy number variation in the gene region of HYAL2 was reported to be associated with diffuse large B-cell lymphoma, indicating that HYAL2 is functional in the malignancy of B cells." (PMID 28978057, 2017). "There was also a trend for low HYAL2 expression in the most aggressive, grade 3 tumors, a result resembling that in diffuse large B-cell lymphomas (DLBCLs)." (PMID 19435493, 2009).
dysplastic nevi (2 papers, 2013 to 2016). "Previously we showed that HYAL2 expression is elevated in dysplastic nevi and the expression is also elevated in locally invasive and metastatic melanomas." (PMID 27184066, 2016).
fibrosarcoma (2 papers, 2013 to 2022). A malignant mesenchymal fibroblastic neoplasm affecting the soft tissue and bone. "This is also the case in fibrosarcoma cells, as FGF-2 stimulates in a cell-specific manner the migration capability of fibrosarcoma cells by decreasing HYAL-2 expression in HT1080 cells and by increasing HAS1 and -2 expressions." (PMID 24083250, 2013).
inflammatory bowel disease (2 papers, 2021 to 2025). A spectrum of small and large bowel inflammatory diseases of unknown etiology. "Another non-oncological GI disease process, inflammatory bowel disease (IBD), is associated with a reduction in HYAL2 in patients’ platelets, which has been shown to regulate trans-endothelial mononuclear cell migration in colonic tissue of IBD patients." (PMID 33809827, 2021).
kidney cancer (2 papers, 2008 to 2010). Primary or metastatic malignant neoplasm involving the kidney. "In contrast, recent findings have shown that the expression of HYAL1 and HYAL2 genes is significantly decreased in lung and kidney cancer samples." (PMID 20875124, 2010). "Our findings are also similar to those of lung and kidney cancer samples in which a major down-regulation of HYAL1 and HYAL2 genes has been shown." (PMID 20875124, 2010).
lung squamous cell carcinomas (2 papers, 2008 to 2014). "As expected for tumour suppressor genes HYAL1 and HYAL2 were down-expressed in 15 fresh lung squamous cell carcinomas (100%) and clear cell RCC tumours (60–67%)." (PMID 18725949, 2008).
orofacial clefting (2 papers, 2017 to 2022). "In the current study, we identify mutations in the gene HYAL2 as a new genetic cause of orofacial clefting in humans and mice and describe the first molecular basis for cor triatriatum sinister in humans." (PMID 28081210, 2017). "Taken together our findings identify a new genetic cause of orofacial clefting in humans and mice, and define the first molecular cause of human cor triatriatum sinister, illustrating the fundamental importance of HYAL2 and hyaluronan turnover for normal human and mouse development." (PMID 28081210, 2017). "Here, we describe mutations in the HYAL2 gene as a cause of syndromic orofacial clefting." (PMID 28081210, 2017).
osteoarthritis (2 papers, 2004 to 2017). A noninflammatory degenerative joint disease occurring chiefly in older persons, characterized by degeneration of the articular cartilage, hypertrophy of bone at the margins and changes in the synovial membrane. "The aims of this study were to investigate the effects of hyaluronidase 2 (Hyal2) knockdown in articular cartilage on the development of osteoarthritis (OA) using genetic manipulated mice." (PMID 28765635, 2017). "The aims of the current study were to analyze the roles of Hyal2 in the development and progression of osteoarthritis using non-treated aged mice (natural course) and joint instability OA models of mice, in addition to an explant culture inflammation model of articular cartilage." (PMID 28765635, 2017).
Stroke (2 papers, 2020 to 2025). Sudden impairment of blood flow to a part of the brain due to occlusion or rupture of an artery to the brain. "Elevated HAS1, HAS2, HYAL1, and HYAL2 were also found in post-mortem brain tissue of stroke patients, and elevated HYAL1 was observed in serum from stroke patients." (PMID 41586378, 2025). "Similarly, Hyal1, Hyal2, and Has2 mRNAs become upregulated in peri-infarct tissues in a rat model of stroke induced by occlusion of the middle cerebral artery." (PMID 41586378, 2025).
angina (1 paper, 2021). "We evaluated the platelet’s HYAL2 (pltHYAL2) levels on I) stable angina (SA) and II) ACS patients, furtherly sub-grouped in Intact-Fibrous-Cap (IFC) and Ruptured-Fibrous-Cap (RFC), according to Optical Coherence Tomography." (PMID 33733989, 2021).
Arthritis (1 paper, 2004). Inflammation of a joint. "The message expression of hyaluronan synthase-1 and -2 in the synovium of both types of arthritis was significantly less than in the control synovium, whereas that of hyaluronidase-2 in the synovium of both arthritides was significantly greater than in the control synovium." (PMID 15535829, 2004).
astrocytomas (1 paper, 2018). "Our results indicate that especially HAS2 and to a lesser extent HYAL2 and HAS1 are involved in the progression of diffusely infiltrating astrocytomas." (PMID 29914429, 2018).
bladder cancer (1 paper, 2022). "More recently, it was demonstrated that monocytic MDSCs in patients with bladder cancer, in contrast to healthy donors, frequently co-express membrane-bound enzyme hyaluronidase 2 (Hyal2)." (PMID 35528727, 2022). "Similar to human bladder cancer, CD33+ in a patient with RCC, also co-expressed membrane-bound enzyme Hyal2." (PMID 35528727, 2022).
breast tumor (1 paper, 2015). "NHE1 and Hyal2 have also been shown to form a complex with CD44s to promote breast tumor cell invasiveness." (PMID 25716319, 2015).
cartilage development disorders (1 paper, 2019). "This idea is supported by the observation that Hyal2 deficient mice show cartilage development disorders and osteoarthritic like cartilage degeneration." (PMID 30621194, 2019).
cleft palate (1 paper, 2017). Cleft palate is a fissure type embryopathy that affects the soft and hard palate to varying degrees. "Consistent with the clinical presentation in affected individuals, investigations of Hyal2-/- mice revealed craniofacial abnormalities, including submucosal cleft palate." (PMID 28081210, 2017).
cor triatriatum (1 paper, 2017). "Our findings demonstrate that a deficiency of the HA-degrading enzyme HYAL2 is a novel cause of syndromic CLP in humans and SMCP in mice, and define the first molecular explanation for cor triatriatum sinister in humans." (PMID 28081210, 2017).
cutaneous melanoma (1 paper, 2016). A primary melanoma arising from atypical melanocytes in the skin. "In the present study our aim was to investigate whether HAS1-2 or HYAL2 have prognostic value for cutaneous melanoma." (PMID 27184066, 2016). "Our previous work showed that decreased expression of hyaluronan in the cutaneous melanoma is due to decreased expression of HAS1 and HAS2 and increased expression of HYAL2." (PMID 27184066, 2016).
endometrioid ovarian cancer (1 paper, 2022). "For patients with endometrioid ovarian cancer expression of HYAL2 (HR = 0.17, p-value = 5.00 × 10–4) and PH20 (HR = 0.3, p-value = 0.015) was associated with better PFS." (PMID 35767191, 2022).
endometriosis (1 paper, 2024). The growth of functional endometrial tissue in anatomic sites outside the uterine body. "Existing studies have indicated that ACE, HPSE, HYAL2, LMAN2, and SULF2 are related to endometriosis." (PMID 39062484, 2024).
frontonasal dysplasia (1 paper, 2022). A group of rare bone development disorders characterized by an array of abnormalities affecting the eyes, forehead, and nose, and linked to midfacial dysraphia. "Overall, the craniofacial appearance of individuals carrying pathogenic HYAL2 variants resembles the phenotypic spectrum of frontonasal dysplasias, with overlapping features, including hypertelorism, nasal anomalies, and midline orofacial clefts." (PMID 34906488, 2022).
glioma (1 paper, 2023). A benign or malignant brain and spinal cord tumor that arises from glial cells (astrocytes, oligodendrocytes, ependymal cells). "In conclusion, our observations revealed that HYAL2 overexpression in gliomas is associated with prognosis." (PMID 37568202, 2023). "Briefly, all of these results revealed that high expression of HYAL2 was closely associated with multiple malignant clinical characteristics of glioma and also serves as a predictive factor for glioma prognosis." (PMID 37568202, 2023). "Given that HYAL2 might act as a risk factor for glioma prognosis, we wanted to determine whether disturbing HYAL2 expression could exhibit a therapeutic outcome in glioma." (PMID 37568202, 2023). "Moreover, in terms of glioma histology classification, HYAL2 overexpression was closely associated with the histology of glioma." (PMID 37568202, 2023). "Moreover, we found that HYAL2 overexpression is associated with multiple glioma clinical traits and acts as a key indicator for glioma prognosis." (PMID 37568202, 2023). "Overall, these univariate and multivariate Cox analysis data suggested that increased HYAL2 expression may represent an independent risk factor for glioma patient prognosis." (PMID 37568202, 2023). "In addition, to explore the clinical diagnostic value of HYAL2 for glioma, receiver operating characteristic (ROC) curves were generated to evaluate the accuracy of HYAL2 as a glioma prognostic factor in TCGA and CGGA (mRNA-array_301, mRNAseq_325 and mRNAseq_693) datasets." (PMID 37568202, 2023). "Then, the mRNA expression and protein level of HYAL2 was determined by qRT-PCR, Western blot and Immunohistochemical staining in glioma cells and glioma tissues, respectively." (PMID 37568202, 2023). "HYAL2 expression was increased in glioma tissues compared with normal tissues in the TCGA database; moreover, in the CGGA database, the expression of HYAL2 was positively correlated with the grade of glioma." (PMID 37568202, 2023). "We found that among the six HAases, only HYAL2 expression was markedly overexpressed in glioma, and the HYAL2 expression was statistically significant in glioma relative to normal brain tissue." (PMID 37568202, 2023). "SiHYAL2 was utilized to treat the U251 glioma cell line, and flow cytometry was performed to detect the effect of HYAL2 knockdown on the glioma cell cycle." (PMID 37568202, 2023). "In the present study, we confirmed that Hyaluronidase 2 (HYAL2) is abnormally overexpressed in glioma." (PMID 37568202, 2023). "Taken together, these data supported that HYAL2 expression was abnormally increased in glioma and negatively correlated with glioma prognosis." (PMID 37568202, 2023). "Subsequent studies demonstrated that targeting HYAL2 can induce glioma cell apoptosis and arrest the cell cycle in the G1 phase." (PMID 37568202, 2023). "Because HYAL2 was overexpressed in glioma and closely related to a poor prognosis in glioma patients, we further investigated the correlation of HYAL2 expression with the clinical characteristics of glioma patients." (PMID 37568202, 2023). "In TCGA and GEPIA databases, we found that among the 6 human hyaluronidases (HYAL1, HYAL2, HYAL3, HYAL4, HYALP1, SPAM1), only HYAL2 expression was highest in glioma." (PMID 37568202, 2023). "HYAL2 knockdown reduced glioma cell viability and induced glioma cell apoptosis and cell cycle arrest." (PMID 37568202, 2023). "In view of this conclusion, in our next study, we will further investigate the mechanism by which HYAL2-mediated HA degradation promotes glioma progression." (PMID 37568202, 2023). "The MTT, EdU and Colony formation assay were used to measure the effect of HYAL2 knockdown on glioma." (PMID 37568202, 2023). "We found that HYAL2 expression in gliomas was abnormally high and closely related to the prognosis of glioma patients." (PMID 37568202, 2023). "Next, TCGA and CGGA database were further used to explore the correlation of HYAL2 expression with glioma prognosis." (PMID 37568202, 2023).
glioma (continued). "The GSEA enrichment analysis was performed to explore the potential pathway regulated by HYAL2 in glioma, in addition, the HYAL2-regulated signaling pathways were detected by flow cytometry and Western blot." (PMID 37568202, 2023). "Due to HYAL2 is overexpressed in multiple cancers including glioma, we aimed to further demonstrate the correlation of HYAL2 with glioma." (PMID 37568202, 2023). "In human specimens, the Western blotting and immunohistochemical staining results indicated that the protein expression levels of HYAL2 were increased in glioma tissues relative to normal brain tissues and it was positively correlated with glioma grade." (PMID 37568202, 2023). "In the TCGA and CGGA databases (mRNA-array_301, mRNAseq_325 and mRNAseq_693), the GSEA results showed that high HYAL2 expression resulted in significant enrichment of the cell cycle and apoptosis pathways in glioma." (PMID 37568202, 2023). "Targeting HYAL2 could inhibit glioma progression by inducing glioma cell apoptosis and cell cycle arrest." (PMID 37568202, 2023). "These evidences supported that HYAL2 was abnormally overexpressed in glioma." (PMID 37568202, 2023). "Considering these findings, we hypothesized that targeting HYAL2 could induce apoptosis and inhibit glioma cell proliferation by arresting the cell cycle in G1 phase, ultimately restraining glioma growth." (PMID 37568202, 2023). "In the present study, our results confirmed that among the six hyaluronidases (HYAL1, HYAL2, HYAL3, HYAL4, HYALP1, SPAM1), only HYAL2 was overexpressed in glioma patients, and HYAL2 overexpression was negatively correlated with the survival time of glioma patients." (PMID 37568202, 2023). "In this research, we clearly confirmed that the expression of HYAL2 is abnormally increased in glioma samples in the TCGA, CGGA databases and glioma specimens, and that the HYAL2 expression level is significantly negatively correlated with the glioma patient’s survival time." (PMID 37568202, 2023). "We found that the green fluorescence intensity could be strongly decreased by siHYAL2 in glioma, suggesting that HYAL2 knockdown could decrease glioma proliferation." (PMID 37568202, 2023). "Collectively, these observations suggest that HYAL2 overexpression could promote glioma progression." (PMID 37568202, 2023). "We next explored the relationship between HYAL2 expression and glioma patient survival time, and Kaplan‒Meier survival analysis demonstrated that glioma patients with high HYAL2 expression had a shorter survival time in the TCGA and CGGA datasets (mRNA-array_301, mRNAseq_325 and mRNAseq_693)." (PMID 37568202, 2023). "Additionally, the reliability of CMap as a potential drug prediction tool for the disease has been confirmed, and in the next study, we will focus on the effects of these small molecule drugs as HYAL2 inhibitors in glioma." (PMID 37568202, 2023). "HYAL2 expression was higher in recurrent glioma than in primary glioma." (PMID 37568202, 2023). "Subsequent univariate, multivariate Cox and ROC analysis results showed that the expression level of HYAL2 could act as a prognostic factor for glioma, and it was also correlated with a variety of clinical traits in glioma patients, including histology, IDH status, and 1p19q codeletion status." (PMID 37568202, 2023). "Moreover, high HYAL2 expression can be used as a key indicator for glioma patient prognosis." (PMID 37568202, 2023). "In addition, in this study, we demonstrated that HYAL2 was unusually highly expressed in glioma." (PMID 37568202, 2023). "Moreover, the Western blotting results showed that HYAL2 knockdown decreased the relative levels of the cell cycle-associated proteins CCNB1 and CCND1 in glioma cells, further suggesting that silencing HYAL2 could induce cell cycle arrest in glioma." (PMID 37568202, 2023). "Thus, treatments that disrupt HA catabolism by altering HYAL2 expression may serve as effective strategies for glioma treatment." (PMID 37568202, 2023).
glioma (continued). "Finally, small molecule compounds targeting HYAL2 in glioma were screened by Cmap analysis." (PMID 37568202, 2023). "Then, we demonstrated that HYAL2 knockdown could affect the cell cycle and apoptosis in glioma." (PMID 37568202, 2023). "Western blotting results indicated that HYAL2 knockdown induced Bcl-2 downregulation, an anti-apoptotic protein, in glioma cells; more importantly, HYAL2 silencing increased the level of BAX, a pro-apoptotic protein, in glioma cells." (PMID 37568202, 2023). "Therefore, we speculated that it is highly likely that the overexpression of HAS3 promotes the abnormal biosynthesis of HA, and then excess accumulated HMW-HA can be further degraded into LMW-HA by HYAL2, which ultimately accelerates the malignant progression of glioma." (PMID 37568202, 2023). "Subsequently, siRNA was used to knockdown HYAL2 in U251 and LN229 glioma cell lines." (PMID 37568202, 2023). "We further explored the possible signaling pathway by which HYAL2 affects glioma by GSEA, meanwhile, found that HYAL2 could significantly affect apoptosis and the cell cycle in glioma." (PMID 37568202, 2023). "Therefore, we assessed the relative mRNA expression level of HYAL2 in four glioma cell lines (U251, LN229, U87, A172) and HUVECs, which showed that the expression of HYAL2 in glioma cell lines was increased significantly compared with that in HUVECs." (PMID 37568202, 2023).
head and neck squamous cell carcinoma (1 paper, 2017). A squamous cell carcinoma that arises from any of the following anatomic sites: lip and oral cavity, nasal cavity, paranasal sinuses, pharynx, larynx, and salivary glands. "This is in agreement with previous studies publishing decreased HYAL2 methylation in the peripheral blood in the patients with head and neck squamous cell carcinoma compared to controls." (PMID 28978057, 2017).
hearing loss (1 paper, 2022). "However, screening for hearing loss in all patients at diagnosis is recommended because we cannot exclude an independent association with HYAL2 deficiency." (PMID 34906488, 2022).
injury (1 paper, 2017). Damage inflicted on the body as the direct or indirect result of an external force, with or without disruption of structural continuity. "Functional significance of the Hyal-2/WWOX signaling was tested in a traumatic brain injury model in rat, and the signaling revealed a critical role of nuclear Hyal-2 and WWOX in causing apoptosis under stress conditions." (PMID 27845895, 2017).